C1GALT1C1L (C1GALT1 specific chaperone 1 like)
Tractability: Antibody: UniProt predicts a signal peptide or a membrane-spanning region. PROTAC: ubiquitination databases record sites on it.
Gene: Protein-coding gene on chromosome 2 (43,675,151 to 43,676,429, reverse strand). Ensembl gene ENSG00000223658.
Subcellular location: Membrane
Gene Ontology:
Biological process: protein O-linked glycosylation
Cellular component: membrane
Genetic constraint (gnomAD): Loss-of-function variants: 2 observed, 2.27 expected, observed/expected ratio (o/e) 0.88, 90% interval 0.33 to 1.85. That is too few expected variants to judge how well the gene tolerates losing a copy. Missense variants: 444 observed, 395.79 expected, observed/expected ratio (o/e) 1.12, 90% interval 1.04 to 1.21. Synonymous variants: 148 observed, 141 expected, observed/expected ratio (o/e) 1.05, 90% interval 0.92 to 1.2.
Homologues: Orthologues: chimpanzee C1GALT1C1L (98% identical), macaque C1GALT1C1L (96% identical), tropical clawed frog c1galt1c1 (54% identical), zebrafish c1galt1c1 (45% identical), Drosophila melanogaster CG34057 (22% identical), Drosophila melanogaster CG18558 (22% identical), Drosophila melanogaster CG2983 (20% identical), Drosophila melanogaster tgy (20% identical), Caenorhabditis elegans C16D9.6 (19% identical), Caenorhabditis elegans Y38C1AB.5 (18% identical), Caenorhabditis elegans bus-4 (17% identical), Caenorhabditis elegans C02H6.1 (16% identical), and 3 more. Paralogues in human: C1GALT1C1 (64% identical), C1GALT1 (24% identical).
Diseases named in the same sentence as C1GALT1C1L in open-access papers:
C1GALT1C1L is named in the same sentence as 2 diseases in open-access papers, as found by Europe PMC text mining. Sharing a sentence is not in itself a finding about the gene and the disease. The quoted sentences say what the papers report.
glioma (1 paper, 2024). A benign or malignant brain and spinal cord tumor that arises from glial cells (astrocytes, oligodendrocytes, ependymal cells). "Finally, functional experiments were performed to evaluate the roles of risk genes in the cell viability of glioma cells, which demonstrated that silencing BGN, SDC1, SERPINA1, TUBA1C, C1GALT1C1L and SPTBN5 could inhibit the growth and viability of glioma cells." (PMID 38396140, 2024). "Moreover, functional experiments were performed to evaluate the roles of risk genes in the cell viability and cell number of glioma U87 and U251 cells, which demonstrated that silencing BGN, SDC1, SERPINA1, TUBA1C, C1GALT1C1L and SPTBN5 could inhibit the growth and viability of glioma cells." (PMID 38396140, 2024).
C1GALT1C1L also shares sentences with these, for which no sentence is quoted: osteosarcoma (1 paper).